CXCR3 (C-X-C motif chemokine receptor 3)
Diseases named in the same sentence as CXCR3 in open-access papers (continued):
Sharing a sentence is not in itself a finding about the gene and the disease.
gastric cancer (24 papers, 2014 to 2025). A primary or metastatic malignant neoplasm involving the stomach. "Although the CXCR3 axis has been implicated in osteosarcoma, colorectal, breast, cervical, and gastric cancers, to our knowledge this is the first suggestion of such a relationship in HPVOPC." (PMID 37686653, 2023). "Higher CXCR3 expression is correlated with increased CD8+ and CD4+ cell infiltration, and low CXCR3 expression is associated with poor prognosis in gastric cancer." (PMID 31696204, 2019). "While high CXCR3 expression in glioblastoma, colorectal, and breast cancer is associated with poor prognosis, it correlated with better outcomes in patients with gastric cancer." (PMID 30319622, 2018). "Low CXCR3 expression is associated with worse prognosis in renal cell carcinoma and gastric cancer." (PMID 31696204, 2019). "Low CXCR3 expression was associated with unfavorable prognosis in gastric cancer." (PMID 31696204, 2019). "Previous research on gastric cancer showed that the activation of the CXCL9/CXCR3 axis upregulated the expression of PD-L1 through the STAT and PI3K-Akt pathways." (PMID 38957805, 2024). "Higher CXCR3 expression has been reported to be related to a good prognosis of renal and gastric cancer." (PMID 36750966, 2023). "Some evidence suggests that CXCR3 secreted by immune cells can inhibit the development of gastric cancer through paracrine pathway." (PMID 35768814, 2022). "With respect to cancer, gastric cancer patients with upregulated CXCR3 expression showed better survival." (PMID 34328416, 2021). "Some of these chemokines and receptors, such as CXCL13, CCL4, CCL5, CCR2, CXCR3, and CXCR4, have been experimentally confirmed to be associated with the pathogenesis or prognosis of gastric cancer or other malignancies." (PMID 32685487, 2020). "Patients with low CXCR3 expression show worse prognosis than patients with high CXCR3 expression in clear cell renal cell carcinoma and gastric cancer." (PMID 31696204, 2019). "The expression of PD-L1 and CXCR3 was positively correlated in gastric cancer with a correlation coefficient of 0.211 (P = 0.044), with statistical significance." (PMID 29690901, 2018). "There was a significant positive correlation between the expression of PD-L1 and CXCR3 in gastric cancer patient tissues." (PMID 29690901, 2018). "Furthermore, the expression of CXCR3 on cancer cells reduces polarization into TAMs; a study of gastric cancer patients demonstrated that those who expressed more CXCR3 had a better prognosis." (PMID 39114657, 2024). "Also, previous research has shown that CXCR3 is correlated with decreased M2 macrophage infiltration and a favorable prognosis in gastric cancer." (PMID 36249427, 2022). "We performed immunohistochemistry among 92 specimens of gastric cancer tissue, and we observed that the immune response of PD-L1 was mainly in the cytomembrane of gastric cancer cells, and the immune response of CXCR3 was mainly in the cytoplasm of gastric cancer cells." (PMID 29690901, 2018). "The aim of this study was to explore the correlation of chemokine receptor CXCR3 with M2 macrophage infiltration, various clinicopathological features, and prognosis in patients diagnosed with gastric cancer (GC)." (PMID 31240220, 2019). "PPI network analysis highlighted eight key hub genes (CD80, CCR9, CXCR3, CXCR5, CXCR6, CCR3, CCL20, and CXCL1), revealing their pivotal roles in gastric cancer and H. pylori infection." (PMID 40445003, 2025). "The invasion and migration of gastric cancer cells can be promoted by MMP-2 and MMP-9, which are upregulated by the CXCL10/CXCR3 axis." (PMID 34367971, 2021). "For example, expression levels of CXCR3, CXCR4, and CXCR5 displayed a marked increase in gastric cancer and were significantly correlated to the prognosis of patients." (PMID 34337085, 2021).
gastric cancer (continued). "used gastric cancer cells transfected with CXCL10 expression and T cells induced with CXCR3 expression for the construction of a tumor‐immune coculture system and directly observed the dose‐dependent effect of T cell migration and infiltration and CXCL10–CXCR3 interaction intensity." (PMID 38045830, 2023).
hepatocellular carcinoma (24 papers, 2014 to 2025). A malignant tumor that arises from hepatocytes. "IL17+ Th cells selectively recruit CXCR3+ B cells which can induce tumor-promoting macrophage polarization and facilitate hepatocellular carcinoma development." (PMID 39744696, 2025). "In a separate hepatocellular carcinoma cohort, we replaced the stromal component with specific immune cell types—CXCR3+CD68+ or CD8+—to profile their spatial relationships with CXCL9+CD68+ cells." (PMID 39965007, 2025). "For example, the selective recruitment of CXCR3(+) B cells by pro-inflammatory IL-17 induced protumorigenic M2 macrophage polarization in human hepatocellular carcinoma." (PMID 39548525, 2024). "In contrast, it has been observed that human breast, ovarian, colorectal, and hepatocellular carcinomas exhibit the recruitment of CXCR3+FOXP3+ Tregs inside the TME." (PMID 38730579, 2024). "High CXCL9 and CXCL10 levels inhibit cytolytic CD8+ T cell expression of CXCR3 in hepatocellular carcinomas, and this, in turn, limits lymphocyte recruitment and tumor defense." (PMID 26462153, 2015). "To test whether CXCL10 might directly influence tumor cell proliferation as tumor cells can express CXCR3, we performed a proliferation assay with the human hepatoma cell line HUH7." (PMID 35897689, 2022). "In this study, CXCL11 signaling through CXCR3 led hepatocellular carcinoma cells to acquire and maintain properties like self-renewal, tumorigenicity, and chemoresistance via activation of the ERK1/2 pathway, and CXCL11 knock-down reduced tumorgenicity in a mouse xenograft model." (PMID 36118530, 2022). "This augmentation is attributed to the mobilization of CD8+ T cells into the tumor, facilitated by the CXCL10/CXCR3 axis, mainly observed in hepatocellular carcinoma (HCC)." (PMID 39881333, 2025). "elucidated that the chemokine receptor CXCR3 orchestrates the polarization of TAMs, effectively constraining tumor growth and angiogenesis in murine hepatocellular carcinoma (HCC)." (PMID 39206194, 2024). "IRF1 was found to regulate C-X-C motif chemokine 10 (CXCL10)/chemokine receptor 3 (CXCR3) signaling axis, thereby further activating antitumor immunity in hepatocellular carcinoma (HCC)." (PMID 35664436, 2022). "We newly found that proinflammatory IL-17+ cells in the peritumoral stroma stimulated hepatoma cells to produce CXCL9, CXCL10 and CXCL11, which in turn led to CXCR3+ B-cell recruitment, maturation and IgG production." (PMID 27853178, 2016). "However, in hepatocellular carcinoma studies, CXCL9 binds to the receptor subtype CXCR3 and activates the rhCXCL9-induced p-ERK1/2-MMP2/MMP9 pathway, enhancing the migration and invasion of CD133+ hepatocellular carcinoma." (PMID 36479091, 2022).
lung carcinoma (24 papers, 2011 to 2025). "Some of the reasons implicated in the differential involvement of CXCR3 in lung cancer include differences in damaged tissue, the level of inflammation, and the types of immune cells produced as a result of cancer types and organs involved." (PMID 36164329, 2022). "In a lung cancer model, radiation has been shown to enhance CXCR3+ T cell activation in an IFNγ-dependent manner, via CXCL10 and ICAM-1." (PMID 38786066, 2024). "Our findings indicate that autocrine and paracrine activations of the CXCL10/CXCR3 pathway contribute to early EGFR-TKI resistance in EGFR-mutant lung cancer." (PMID 36612121, 2022). "We demonstrate that a CXCL10/CXCR3 pathway is activated in EGFR-mutant lung cancer cells when cocultured with activated PBMCs and exposed to EGFR-TKI treatment." (PMID 36612121, 2022). "Studies show that disrupting CXCR3 signaling using chemical antagonists results in lower tumor burden in human lung cancer due to reduced cell proliferation and survival as well as increased caspase-independent cell death." (PMID 32161595, 2020). "A 2012 study demonstrates that CXCL10 attracts CXCR3-expressing tumor cells to the bone, though omitting its connection with lung cancer." (PMID 33262947, 2020). "Meanwhile, only CXCR3 decreased in CD8+ T cells of patients with lung cancer." (PMID 36688994, 2023). "Importantly, elevated CXCL10/CXCR3 signaling was recapitulated in a transgenic lung cancer mouse model." (PMID 36612121, 2022). "It is thus possible that CXCL10 in the bone stroma may upregulate CXCR3 production in lung cancer cells, which in turn became more attracted to the bone." (PMID 33262947, 2020). "Therefore, low expression of CXCR3 of T lymphocytes in a patient with lung cancer may be a target for exchanging tumors from “cold tumors” to “hot tumors” for improving clinical immunotherapeutic efficacy." (PMID 36688994, 2023). "Thus, we hypothesize that CXCL10/CXCR3/Src activation may mediate an oncogenic signaling pathway in EGFR-mutant lung cancer cell lines." (PMID 36612121, 2022). "Compared with PBNs in lung carcinomas patients, increased levels of CCR5, CCR7, CXCR3, and CXCR4 are expressed in TANs, whereas CXCR1 and CXCR2 expression are downregulated." (PMID 41254689, 2025). "Specifically, we found that CXCR3 decreased in the CD4+ T and CD8+ T cells in patients with lung cancer." (PMID 36688994, 2023). "We further demonstrated that CXCR3 and CXCL10 decreased in the CD8+ T cells and nonCD8+ PBMCs, respectively, in the patients with lung cancer that expressed lower reactivation as co-cultured with A549 cells." (PMID 36688994, 2023). "Meanwhile, we found that CXCR3 and LFA-1 decreased in CD4+ T cells of patients with lung cancer (N = 6) compared to healthy volunteers (N = 14)." (PMID 36688994, 2023). "Meanwhile, we also demonstrated that decreased CXCR3, a receptor for CXCL9/10, in the CD8+ T cells of patients with lung cancers exhibited lower motility compared to healthy CD8+ T cells." (PMID 34680466, 2021). "The CXCR3 expressional ratio was similar to that in subtypes of CD8+ T cells between a healthy volunteer and a patient with lung cancer." (PMID 34680466, 2021). "We found that CXCR3 and PD-1 were down-regulated and up-regulated, respectively, in the peripheral blood CD8+ T cells in patients with lung cancer (n = 4 vs. healthy n = 3, both p < 0.05), which exhibited reduction of cell motility (p < 0.05)." (PMID 34680466, 2021). "Lung cancer-derived exosomes inhibit the migration of DCs to lymph nodes by broadly decreasing the C-C/C-X-C chemokine receptors, especially CCR6, CCR7, and CXCR3, on DCs." (PMID 34572829, 2021). "The activation markers GZMB, PRF-1, and IFNγ, migration marker CD183 (CXCR3), and inhibitory marker CD274 (PD-1), were measured and compared in CD8+ T cells with A549 co-cultured, chemokines treated, and patients with late-stage lung cancer." (PMID 34680466, 2021).
lung carcinoma (continued). "Compared to circulating blood neutrophils, TANs isolated from early-stage human lung cancer exhibited an activated phenotype, characterized by low CD62L and high CD54 expression, along with a distinct chemokine receptor profile including CCR5, CCR7, CXCR3, and CXCR4." (PMID 41254689, 2025). "High expression of the BC-specific ICD-derived metagene signature (TNF/CXCR3/P2RX7/CASP1/NLRP3/IL1B/LY96/CD4+/CD8+A/CD8+B/PRF1/IFNG/IL17A/IL17RA) is associated with prolonged overall survival (OS) in BC and OC patients but not in lung cancer patients." (PMID 37445860, 2023). "By releasing chemokine receptors including CXCR3/4 and CCR5/7, and secreting pro-inflammatory cytokines, notably IL-6, TANs play a pivotal role in the pathogenesis of lung cancer." (PMID 38339264, 2024).
lymphoma (23 papers, 2013 to 2025). A malignant (clonal) proliferation of B- lymphocytes or T- lymphocytes which involves the lymph nodes, bone marrow and/or extranodal sites. "Additionally, CXCR3+%, PD-L1+CXCR3+%, and PD-1+CXCR3+% had a significant association with lymphoma recurrence (r = 0.645, P < 0.001; r = 0.676, P < 0.001; r = 0.310, P = 0.006)." (PMID 36726488, 2023). "High expressions of CXCL9, along with CXCR3, were seen in thyroid and gastric marginal zone lymphoma and also mucosa associated lymphoid tissue type lymphoma, which were speculated to be associated with autocrine function and the migration of lymphoma cells." (PMID 24278236, 2013). "Case reports have described the expression of CXCL9 on lymphoma cells and its receptor CXCR3 on endothelial cells, as well as in other instances, such as CXCR4 expression on lymphoma cells and its ligand CXCL12 on the endothelium." (PMID 40723240, 2025). "Posttherapy 34 lymphoma patients with extranodal involvement were characterized by higher percentages of peripheral CXCR3 positive lymphocytes than those in posttherapy 44 patients without extranodal involvement (median: 78% vs. 26%, P < 0.001)." (PMID 36726488, 2023). "Compared to healthy controls, newly diagnosed lymphoma patients had higher PD-L1+CXCR3+% and PD-1+CXCR3+% (32% vs. 1.1%; 10% vs. 0.7%, P < 0.001)." (PMID 36726488, 2023). "Data revealed that CXCR3+%, PD-L1+CXCR3+%, and PD-1+CXCR3+% positively correlated with lymphoma stages (r = 0.498, P < 0.001; r = 0.437, P < 0.001, r = 0.333, P = 0.002)." (PMID 36726488, 2023). "The findings presuppose that CXCR3/CD36 and PDL1/PD-1 coexpression have a crucial role in lymphoma development, suggesting using this coexpression as a diagnostic test in managing lymphoma." (PMID 36726488, 2023). "The findings revealed that lymphoma patients' peripheral CXCR3-positive lymphocytes have high PD-L1/PD-1 expression levels." (PMID 36726488, 2023). "Flow cytometric analysis investigated CD36 and CXCR3 expression in peripheral lymphocytes in 78 newly diagnosed lymphoma patients and 50 healthy controls." (PMID 36726488, 2023). "PD-L1/PD-1 coexpression with CXCR3/CD36 in peripheral lymphocytes in lymphoma still needs to be clarified." (PMID 36726488, 2023). "Pretherapy IL-19 levels, CXCR3+%, and PD-L1+CXCR3+% in lymphoma patients with recurrence were statistically higher than in the PR patients (P < 0.001)." (PMID 36726488, 2023). "There was a high reduction in EFS in lymphoma patients with high percentages of pre- and posttherapy CXCR3+ lymphocytes (P < 0.001)." (PMID 36726488, 2023). "The coexpression of PD-L1/PD-1 with CXCR3/CD36 on circulating lymphocytes was analyzed by flow cytometry in 78 lymphoma patients before and after therapy and in 50 healthy controls." (PMID 36726488, 2023). "Other studies found that individuals with various forms of lymphoma had a higher percentage of peripheral CD36 and CXCR3+ lymphocytes, implying that lymphoma patients have an immunological defect." (PMID 36726488, 2023). "Another recent report described a case of post-transplant adult T-cell leukemia/lymphoma in whom CXCR3+CCR4+ T cells were observed." (PMID 26795118, 2016). "The reduced expression of CXCR3 in POD24‐FL may alter T cell‐lymphoma interactions, potentially affecting disease progression." (PMID 40896244, 2025). "Another scenario might be due to the PD-L1+CXCR3 and PD-1+CXCR3 cell-mediated tolerance state, enabling extranodal involvement in lymphoma." (PMID 36726488, 2023). "PD-L1+CXCR3+ lymphocytes and serum IL-19 might play a more important role in poor clinical behavior in lymphoma." (PMID 36726488, 2023). "The results might be the outcome of the immune system and lymphoma interaction, assuming that PD-L1/PD-1 coexpression with CXCR3 positive lymphocytes is engaged in tumor invasion and extranodal involvement in lymphoma." (PMID 36726488, 2023).
lymphoma (continued). "Interestingly, we did not observe any substantial differences between GC-B and the lymphoma entities for the B-cell homeostatic chemokine receptors, CXCR3, CXCR4, and CXCR5." (PMID 35887224, 2022). "To investigate whether the dissemination of lymphoma cells is dependent on the expression of chemokine receptors, we examined the expression of the chemokine receptors CXCR3, CCR4, CCR5 and CCR1 in primary cases of ALCL and cHL by immunohistochemistry." (PMID 31581676, 2019). "CXCR3 has been shown to regulate the accumulation of CD27high NK cells in subcutaneous lymphoma." (PMID 28955340, 2017). "Moreover, CXCR3 plays a role in mediating the interaction between T cells and lymphoma cells." (PMID 40896244, 2025). "Therefore, CXCR3 knockout for disrupting this migration axis may improve homing to other tissues, in cases where the ligands are irrelevant in the lymphoma environment." (PMID 38769377, 2024). "PD-L1/PD-1 coexpression with CXCR3/CD36 could significantly impact clinical lymphoma activity." (PMID 36726488, 2023). "PD-L1+CXCR3+ and PD-1+CXCR3+ lymphocytes might be involved in inferior prognosis in lymphoma." (PMID 36726488, 2023). "In addition, we observed co-expression of immune mediators, such as interferons and their targets (IFNA1-2, IFNA7-8, IFNB1, and IFNG), as well as proinflammatory cytokines (IL-1B and IL12B) and chemokines and their receptors (CXCL9-11 and CXCR3) by CpG(B)-STAT3dODN-treated lymphoma cells (right)." (PMID 29433938, 2018). "In POD24‐FLs, weak CXCR3 and CXCR4 expression was found in 13.33% and 40% of lymphoma cells, with moderate CCR3 and CXCR5, and strong CCR7 in 50%, 70%, and 50%, respectively." (PMID 40896244, 2025). "In non‐POD24‐FLs, weak CCR3, CXCR3, and CXCR4 expression was observed in 50%, 11.8%, and 40% of lymphoma cells, respectively, while moderate CXCR5 and strong CCR7 expression was detected in 68.3% and 50%." (PMID 40896244, 2025). "The current study investigated PD-L1/PD-1 coexpression with CXCR3/CD36 in circulating lymphocytes, serum IL-19 levels, and their correlation with clinical outcome and extranodal involvement in lymphoma." (PMID 36726488, 2023). "High pretherapy CXCR3+% and CD36+% of cells were observed in lymphoma patients than in normal volunteers (median: 40% vs. 11.2%; 13% vs. 4.2%, P < 0.001)." (PMID 36726488, 2023). "In this study, the percentage of peripheral CXCR3 and CD36 positive lymphocytes differed significantly between lymphoma patients and healthy controls." (PMID 36726488, 2023). "Patients with high levels of PD-L1/PD-1 coexpression with CXCR3 and IL-19 had inferior event-free survival (EFS) compared with that in lymphoma patients with low levels." (PMID 36726488, 2023). "The study assessed PD-L1/PD-1 expression in circulating CXCR3 and CD36-positive lymphocytes in lymphoma." (PMID 36726488, 2023). "Although other TFH lymphomas was classified as PTCL-NOS with TFH cells, it expressed mainly T-bet and CXCR3, like PTCL-TBX21 (Th1 cell origin)." (PMID 33990228, 2021). "Deutsch reported that C-C motif chemokine receptors 7 (CCR7), CXCR3, and CXCR7 were more frequently detected in lymphoma cells of HP-positive gastric MALT lymphoma than in inflammatory cells of HP-positive gastritis." (PMID 30999581, 2019). "Next we compared global changes in CXCR3, CCR6 and PD1 expression between normal subjects and patients with lymphoma." (PMID 29293620, 2018). "Since EBV+ lymphomas secrete high quantities of CCL3, CCL4, CCL22, and CXCL10 compared to EBV- lymphoma lines, the high expression of CCR5, CCR4, and CXCR3 on both EBV VST groups may indicate complementary/alternate axes of migratory mechanisms." (PMID 39011042, 2024). "Posttherapy CXCR3+%, PDL-1+CXCR3+%, and PD-1+CXC3+% could diagnose lymphoma patients with extranodal involvement." (PMID 36726488, 2023).